TLR9 (toll like receptor 9)
Diseases named in the same sentence as TLR9 in open-access papers (continued):
Sharing a sentence is not in itself a finding about the gene and the disease.
periodontitis (23 papers, 2012 to 2025). An acute or chronic inflammatory process that affects the tissues that surround and support the teeth. "TLR9 plays a key role in periodontitis, and aberrant expression of TLR9 can be observed in patients with periodontitis, thus TLR9 has the potential to serve as a diagnostic or prognostic biomarker for periodontitis." (PMID 38800469, 2024). "TLR2-/-, TLR4-/-, TLR2&4-/-, and TLR9-/- mice exhibited the reduced alveolar bone loss in various mouse periodontitis models, suggesting that TLRs indeed played an important role in developing discordant oral barrier immunity." (PMID 38015204, 2023). "Cytidine-phosphate-guanosine oligodeoxynucleotide (CpG ODNs) and CD40 ligand (CD40L), which are agonists of Tlr9, suppressed periodontal inflammation and bone loss in the alveolus of WT mice with induced-periodontitis." (PMID 34445604, 2021). "Clinical studies have demonstrated that TLR9 gene and protein expression are increased in gingival tissues associated with periodontitis." (PMID 34070809, 2021). "Our data suggest that TLR9 and autophagy proteins are upregulated in periodontitis associated with RA." (PMID 31737959, 2020). "Our previous studies have shown that inhibition of Ctsk can effectively reduce bone resorption in periodontitis associated with arthritis, and have also found a link between Ctsk and Toll‐like receptor 9 (TLR9)." (PMID 31737959, 2020). "Although pathogenesis and pathological mechanism of periodontitis are different from those diseases, these studies provide us reasons for further investigating the underlying TLR9-independent mechanism of CpG in periodontitis." (PMID 29791566, 2018). "In vivo evidence shows that TLR9-deficient (TLR9/) mice are resistant to periodontitis." (PMID 38800469, 2024). "in addition the distribution of TLR9 haplotypes and TLR9 (T1486C) genotypes may be associated with chronic periodontitis." (PMID 38800469, 2024). "Meanwhile, TLR9-deficient mice are resistant to periodontitis." (PMID 36685503, 2022). "Indeed, specific polymorphisms were observed in the promoter region of the TLR9 gene in individuals with periodontitis." (PMID 34070809, 2021). "TLR9-deficient mice are also protected against experimental periodontitis, which could be attributed, at least in part, to complement-TLR9 synergy." (PMID 30915073, 2019). "This study aimed to explore the effects of CpG in combination with CD40L on B cell expansion and function, and whether CpG plus CD40L reduce periodontitis inflammation and alveolar bone loss in a TLR9-independent manner." (PMID 29791566, 2018). "Thus, based on the possible similarity between postoperative alveolar bone loss and periodontitis, we assumed that cfDNA- and TLR9-related innate immune responses could be a major inducement for postoperative bone loss after alveolar bone grafting." (PMID 36685503, 2022). "In periodontitis models, a major role of TLR9 signaling cascade is strongly supported by studies showing that TLR9 knockout mice are resistant to experimental periodontitis provoked by oral inoculation of Porphyromonas gingivalis or by ligature placement." (PMID 41357757, 2025). "DNA of the periodontal pathogen Porphyromonas gingivalis promotes its virulence in periodontitis by expressing inflammatory cytokines via the TLR9 signaling pathway." (PMID 38800469, 2024). "TLR9 is present in gingival tissues, and nucleic acids significantly upregulate TLR9 gene expression in patients with periodontitis." (PMID 38800469, 2024). "Recent data suggest that TLR9 is one of the most up-regulated PRRs expressed in chronic periodontitis." (PMID 38800469, 2024). "TLR9 expression was significantly higher in the untreated periodontitis group than in normal mice; both G3@SeHAN and PAMAM-G3 reduced this periodontitis-associated TLR9 expression." (PMID 36207325, 2022).
periodontitis (continued). "We have confirmed that cfDNA can be a major source that enhances periodontal tissue destruction by activating TLR9 pathway, and targeting cfDNA and TLR9 pathway can help ameliorate periodontitis." (PMID 36685503, 2022). "Together, these results demonstrated that G3@SeHANs inhibited TLR9 activation by scavenging periodontitis-derived cfDNA in vitro." (PMID 36207325, 2022). "Nevertheless, our study suggests that TLR9 plays an important role in Ctsk-mediated initiation of periodontitis." (PMID 36104423, 2022). "Given this, we systematically investigated the correlation among cfDNA, TLR9 and periodontitis, thereby fabricating a periodontitis-specific nanoparticle cfDNA scavenger, G3@SeHANs, which effectively alleviated cfDNA-mediated inflammatory alveolar bone loss." (PMID 36207325, 2022). "Inappropriate activation of TLR9 happened in patients with periodontitis, as increased TLR9 levels can be found in their periodontal tissue." (PMID 36685503, 2022). "Saliva and serum from periodontitis patients induced significantly higher TLR9 activation in HEK-Blue TLR9 cells than that from healthy donors." (PMID 36207325, 2022). "It was reported that, compared with wild-type mice, TLR9 knockout mice had less bone resorption and pro-inflammatory factor release in Porphyromonas gingivalis-induced experimental periodontitis." (PMID 36498477, 2022). "The saliva and serum from periodontitis patients enhanced TLR9 activation, but that activation by saliva was much stronger than by serum." (PMID 36207325, 2022). "Our previous studies also confirmed that TLR9 is highly expressed in the lesion area in periodontitis and RA." (PMID 31737959, 2020). "We aimed to explore a novel target, cathepsin K (Ctsk)‐mediated TLR9‐related autophagy, during the progress of periodontitis with RA." (PMID 31737959, 2020). "This study advanced a novel role for Ctsk in TLR9 and autophagy to explain the interaction between periodontitis and RA." (PMID 31737959, 2020). "In conclusion, our research provides a novel role of Ctsk‐mediated, TLR9 and autophagy in the development of periodontitis aggravated by RA." (PMID 31737959, 2020). "Here, we investigated the relationship between Ctsk and TLR9‐related autophagy in the presence of periodontitis and RA." (PMID 31737959, 2020). "Micro‐CT, immunohistochemistry (IHC), Western blot and quantitative real‐time polymerase chain reaction (qRT‐PCR) were used to detect the expression of TLR9‐related autophagy in periodontitis with RA." (PMID 31737959, 2020). "TLR9 can activate pro- and/or anti-inflammatory signaling pathways and mediate inflammatory responses in periodontitis pathogenesis." (PMID 29791566, 2018). "Alveolar bone loss at left (CpG+CD40L injection) and right (PBS injection) palatal gingiva were measured in WT mice and TLR9 KO mice of ligature-induced experimental periodontitis model." (PMID 29791566, 2018). "Our study consisted in CPG plus CD40L local administration in WT mice and TLR9 KO mice with ligature-induced periodontitis model." (PMID 29791566, 2018). "TLR2 activation is critical for human gingival epithelial cells and human macrophages to recognise and respond to T. denticola and both TLR9 and NOD2 have been reported to contribute to P. gingivalis-induced bone loss in an experimental model of periodontitis." (PMID 27035339, 2016). "Cathepsin K is a key modulator of periodontitis-induced bone destruction and may be involved in the immune regulation of periodontitis via the TLR9 signaling pathway." (PMID 37334378, 2023). "In a study on HIV-positive North American patients with periodontitis, 8 SNPs in 6 TLR genes (TLR1 (n = 2), TLR2 (n = 1), TLR4 (n = 1), TLR6 (n = 1), TLR8 (n = 2), and TLR9 (n = 1)) were positively associated with P. gingivalis (2 SNPs), T. denticola (6 SNPs), and T. forsythia (1 SNP)." (PMID 35122548, 2022).
periodontitis (continued). "We first showed that in vitro G3@SeHANs could reduce DNA-mediated TLR9 activation triggered by synthetic DAMPs well as by a collection of complex PAMPs and DAMPs in the periodontitis saliva and periodontitis serum." (PMID 36207325, 2022). "Furthermore, it was shown that elevated TNFAIP3 in gingival tissue is related to decreased periodontitis together with TLR9 activity." (PMID 35570325, 2022). "To investigate the type of periodontitis-derived cfDNA responsible for activating the TLR9, we used cfDNA isolated from periodontitis saliva and serum, genomic DNA (gDNA) and mitochondrial DNA (mtDNA) as part of DAMPs, and CpG DNA as part of MAMPs to stimulate the HEK-TLR9 receptor cells." (PMID 36207325, 2022). "Among them, TLR2, TLR4, and TLR9 play important roles in the development of periodontitis." (PMID 34445604, 2021). "However, in a murine ligature-induced model of periodontitis, knockout of Tlr9 reduced inflammatory infiltration of the gingival tissue and bone loss." (PMID 34445604, 2021). "In periodontitis with RA, TLR9 and autophagy decreased significantly with inhibition of Ctsk." (PMID 31737959, 2020). "The trend of TLR9 expression change was the same in periodontitis with RA and autophagy, which suggested that TLR9 may be closely related to autophagy in periodontitis with RA." (PMID 31737959, 2020). "Consistent with our hypothesis, transfection with AAV‐sh‐Ctsk reduced bone resorption, expression of TLR9 and autophagy status in the periodontitis and comorbid groups." (PMID 31737959, 2020). "Thus, for the first time, our study suggested that local application of CpG plus CD40L inhibit ligature-induced periodontitis in a TLR9-independent manner." (PMID 29791566, 2018). "However, whether and which kind of cfDNA contributes to periodontitis, whether it is through TLR9 mediated proinflammatory pathway, remains unclear." (PMID 36207325, 2022). "Together, these results demonstrated that two cfDNA scavengers, G3@SeHANs and PAMAM-G3, were both able to inhibit periodontitis-related TLR9-mediated cellular proinflammation induced by different types of cfDNA, but also suggested that the mechanism of the inhibition might be different." (PMID 36207325, 2022). "Whether CpG plus CD40L reduce bone loss through TLR9 signaling in experimental periodontitis was not addressed yet." (PMID 29791566, 2018). "The infiltration of macrophages, TLR9, autophagy proteins (TFEB and LC3) and inflammatory cytokines increased in the periodontitis‐with‐RA group and was reduced by the inhibition of Ctsk in the periodontal region." (PMID 31737959, 2020). "We found that cfDNA from periodontitis saliva but not serum, mtDNA but not gDNA, and CpG DNA induced TLR9 activation, and consistently G3@SeHANs reduced all these TLR9 activations, while the soluble PAMAM-G3 only reduced the activation by mtDNA and CpG DNA." (PMID 36207325, 2022). "It is therefore not unreasonable to speculate that TLR9 plays an important role in the pathogenesis of periodontitis." (PMID 36207325, 2022).
Arthritis (21 papers, 2010 to 2024). Inflammation of a joint. "The inflammation score was first calculated, and we found that the TLR9 antagonist attenuated IL-33-induced arthritis in CAIA mice." (PMID 39617790, 2024). "In conclusion, our study demonstrates that TLR9 inhibition ameliorates the outcome of EBV DNA-exacerbated arthritis in an RA mouse model." (PMID 38731877, 2024). "Studies have shown that inhibition of TLR9 prior to disease onset significantly reduces arthritis and almost completely eliminates bone erosion, and reduces serum IL-6, a-1-acid glycoprotein, and rheumatoid factor levels in PIA rats." (PMID 39450183, 2024). "In rats with pristane‐induced arthritis (PIA), TLR9 inhibition before disease onset reduced arthritis significantly and almost completely abolished bone erosion." (PMID 29992753, 2018). "Rats treated with the TLR9 antagonist developed milder clinical signs of arthritis and showed significantly reduced paw swelling on day 25 compared with the control groups." (PMID 29992753, 2018). "Reduction in arthritis was accompanied by reduced levels of IL‐6 and the inflammatory marker alpha‐1‐acid glycoprotein in sera of animals treated with the TLR9 antagonist." (PMID 29992753, 2018). "Agonistic stimulation through TLR4 or TLR9 resulted in the decrease in diabetes, EAE and arthritis symptoms in mice, and the decrease in the expression of TLR9 in humans which led to increased morbidity to SLE." (PMID 28477096, 2017). "We presume that TLR2 and TLR9 can also be activated by viral components (like EBV) in the synovial compartment, a mechanism causing exacerbation of arthritis in susceptible RA patients." (PMID 26759164, 2016). "We comparatively analyzed the expression of TLR1 through TLR9 in synovium during the whole course of arthritis initiation and development to investigate the roles of TLRs systematically and dynamically in a PIA model." (PMID 21708001, 2011). "Additionally, TLR9 knockout (TLR9-/-) mice exhibited lower arthritis scores and attenuated synovial destruction and inflammatory cell infiltration compared with wild-type (WT) mice, which had impaired DC maturation and migration." (PMID 39450183, 2024). "Finally, we evaluated the efficacy of the mouse TLR9 antagonist ODN2088 in mitigating IL-33-induced arthritis in CAIA mice." (PMID 39617790, 2024). "Next we investigated whether the TLR9 inhibitor could affect arthritis when administered therapeutically after disease induction." (PMID 29992753, 2018). "Furthermore, the intermediate reactivation phase of arthritis post each intra‐articular injection (days 8, 15 and 22) was similar between wild‐type and TLR9−/− mice." (PMID 29992753, 2018). "Thus, the plasmid backbone, which contains the CpG motif signaling with TLR9, appears to play a major role in stimulating Treg cells, thereby slowing the progression of arthritis in our CIA model." (PMID 29854762, 2018). "Joint swelling was not affected by TLR9 deficiency in the acute phase of SCW arthritis, that is days 1 and 2 after the first SCW injection." (PMID 29992753, 2018). "It has also been suggested that cathepsin K could ameliorate mycobacteria induced arthritis in rats through suppression of TLR9 signaling in dendritic cells (DCs)." (PMID 20500834, 2010). "Furthermore, a TLR9 antagonist reduced IL-33-induced arthritis in CAIA mice in vivo." (PMID 39617790, 2024). "Therefore, the aim of the study at hand is to assess whether the administration of a TLR9 inhibitor ameliorates the exacerbation of arthritis in an EBV DNA-injected RA mouse model." (PMID 38731877, 2024). "In contrast to SCW‐arthritis, TLR9 deficiency had no influence on K/BxN serum‐transfer arthritis." (PMID 29992753, 2018). "Based on our previous finding that EBV DNA increases the incidence and severity of arthritis in a CIA mouse model, we investigated the potential therapeutic effect of TLR9 inhibition on EBV DNA-exacerbated arthritis." (PMID 38731877, 2024).
Arthritis (continued). "This action maintained the immune balance between Tfr and Tfh cells by regulating the TLR9-MyD88-STAT3 signalling pathway, reducing joint swelling and arthritis scores, and improving joint injury in CIA mice." (PMID 39450183, 2024). "To find out the candidate key TLR, we analyzed TLR1 through TLR9 mRNA expression in the synovium of PIA rats at different time points, including D0 (normal phase), D6 (prearthritis phase), D12 (arthritis onset phase) and D26 (acute arthritis phase)." (PMID 21708001, 2011). "Based on our previous findings linking Toll-like receptor-9 (TLR9) to an EBV DNA-driven surge in IL-17A production, we aimed to examine the therapeutic potential of TLR9 inhibition in EBV DNA-exacerbated arthritis in a collagen-induced arthritis (CIA) mouse model." (PMID 38731877, 2024). "Ablating TLR9 failed to rescue the lethality of DNase II−/− mice and failed to reduce the arthritis of DNase II−/−Ifnar1−/− mice." (PMID 34901991, 2022). "The inhibitory effects of TLR2 and TLR9 in STA pathogenesis can not explain the EFL2’s anti-inflammatory role in arthritis." (PMID 34950033, 2021). "In addition, TLR9/NF-κB mediated inflammation plays a role in the pathogenesis of T2DOP is worthy of further exploration, because inflammation itself is closely related to diabetes and bone diseases, such as arthritis." (PMID 35707851, 2022). "However, in contrast to prophylactic application, therapeutically administered TLR9 inhibitor did not influence the clinical severity of arthritis." (PMID 29992753, 2018). "Thus, TLR9 did not seem to have an influence on incidence and severity of serum‐transfer arthritis." (PMID 29992753, 2018). "However, when the antagonist was administered therapeutically after the onset of arthritis, no protective effects were observed, indicating that PIA becomes independent of TLR9 signaling and T cells once the disease process has been set in motion." (PMID 29992753, 2018). "In addition, the knockout of TLR9 resulted in no progression of arthritis, suggesting that these three TLRs (i.e., TLR2, TLR4, and TLR9) have different relationships with the induction of arthritis and IL-17 production." (PMID 30103522, 2018). "Moreover, in TLR9−/− mice, streptococcal cell wall (SCW)‐induced arthritis was reduced in the T cell‐dependent phase, whereas T cell‐independent serum‐transfer arthritis was not affected." (PMID 29992753, 2018).